SLC29A1 (solute carrier family 29 member 1 (Augustine blood group))
Description:
Uniporter involved in the facilitative transport of nucleosides and nucleobases, and contributes to maintaining their cellular homeostasis. Functions as a Na(+)-independent transporter. Involved in the transport of nucleosides such as adenosine, guanosine, inosine, uridine, thymidine and cytidine. Also transports purine nucleobases (hypoxanthine, adenine, guanine) and pyrimidine nucleobases (thymine, uracil). Also mediates the uptake of nicotinamide; contributes to maintaining nicotinamide homeostasis but also regulated nicotinamide biological roles. Mediates basolateral nucleoside uptake into Sertoli cells, thereby regulating the transport of nucleosides in testis across the blood-testis barrier (By similarity). Regulates inosine levels in brown adipocytes tissues (BAT) and extracellular inosine levels, which controls BAT-dependent energy expenditure.
Synonyms: hENT1; ENT1; AUG
Tractability: Small molecule: an approved drug acts on it; a structure with a bound ligand is known; a high-quality ligand is known; it belongs to a druggable protein family. Antibody: UniProt places it where antibodies can reach, with high confidence; its Gene Ontology location is reachable by antibodies, with high confidence; UniProt predicts a signal peptide or a membrane-spanning region. PROTAC: ubiquitination databases record sites on it; its protein half-life has been measured; a small molecule that binds it is known.
Target class: Electrochemical transporter; SLC28 and SLC29 families of nucleoside transporters; SLC29 Facilitative nucleoside transporter family; Transporter; SLC superfamily of solute carriers
Chemical probes: DIPYRIDAMOLE
Safety:
Unwanted effects reported when the protein is acted on. In parentheses: how it was acted on, where the effect was seen, and who reports it.
anaphylactoid reaction (inhibition; cardiovascular system; source: Urban et al. (2012))
angina pectoris (inhibition; cardiovascular system; source: Urban et al. (2012))
bronchospasm (inhibition; cardiovascular system; source: Urban et al. (2012))
cardiac death (inhibition; cardiovascular system; source: Urban et al. (2012))
dizziness (inhibition; cardiovascular system; source: Urban et al. (2012))
hypotension (inhibition; cardiovascular system; source: Urban et al. (2012))
inhibition of platelet aggregation (inhibition; cardiovascular system; source: Urban et al. (2012))
myocardial infarction (inhibition; cardiovascular system; source: Urban et al. (2012))
peripheral and central vasodilation (inhibition; cardiovascular system; source: Urban et al. (2012))
promotion of sleep (inhibition; cardiovascular system; source: Urban et al. (2012))
seizure (inhibition; cardiovascular system; source: Urban et al. (2012))
stroke (inhibition; cardiovascular system; source: Urban et al. (2012))
transient cerebral ischemia (inhibition; cardiovascular system; source: Urban et al. (2012))
ventricular fibrillation (inhibition; cardiovascular system; source: Urban et al. (2012))
ventricular tachycardia (inhibition; cardiovascular system; source: Urban et al. (2012))
hypertension (source: ClinPGx)
neutropenia (source: ClinPGx)
Gene: Protein-coding gene on chromosome 6 (44,219,245 to 44,236,432, forward strand). Ensembl gene ENSG00000112759.
Subcellular location: Basolateral cell membrane; Apical cell membrane; Cell membrane
Pathways (Reactome):
Drug ADME: Azathioprine ADME; Ribavirin ADME
Transport of small molecules: Transport of nucleosides and free purine and pyrimidine bases across the plasma membrane
Gene Ontology:
Molecular function: adenine transmembrane transporter activity; cytidine transmembrane transporter activity; guanine transmembrane transporter activity; neurotransmitter transmembrane transporter activity; nucleoside transmembrane transporter activity; purine nucleoside transmembrane transporter activity; pyrimidine- and adenosine-specific:sodium symporter activity; uracil transmembrane transporter activity; uridine transmembrane transporter activity
Biological process: adenine transport; adenosine transport; cytidine transport; guanine transmembrane transport; hypoxanthine transport; inosine transport; neurotransmitter transport; nucleobase transport; nucleoside transmembrane transport; nucleoside transport; purine nucleobase transmembrane transport; purine nucleoside transmembrane transport; pyrimidine nucleobase transmembrane transport; pyrimidine-containing compound transmembrane transport; thymine transport; uracil transmembrane transport; uridine transmembrane transport; neurotransmitter uptake; nucleobase-containing compound metabolic process; transport across blood-brain barrier; xenobiotic metabolic process; xenobiotic transmembrane transport; cellular response to glucose stimulus; cellular response to hypoxia; excitatory postsynaptic potential; and 2 more
Cellular component: apical plasma membrane; basolateral plasma membrane; membrane; plasma membrane; postsynapse; presynapse
Genetic constraint (gnomAD): Loss-of-function variants: 19 observed, 41.19 expected, observed/expected ratio (o/e) 0.46, 90% interval 0.32 to 0.68. The upper end of that interval is the gene's LOEUF score, 0.68, which puts it in group 2 of 6, group 1 being the genes least tolerant of losing a copy. Missense variants: 482 observed, 586.5 expected, observed/expected ratio (o/e) 0.82, 90% interval 0.76 to 0.89. Synonymous variants: 227 observed, 238.33 expected, observed/expected ratio (o/e) 0.95, 90% interval 0.85 to 1.06.
Homologues: Orthologues: chimpanzee SLC29A1 (99% identical), rabbit SLC29A1 (89% identical), dog SLC29A1 (88% identical), guinea pig SLC29A1 (87% identical), pig SLC29A1 (87% identical), mouse Slc29a1 (80% identical), rat Slc29a1 (78% identical), zebrafish slc29a1b (65% identical), zebrafish slc29a1a (63% identical), tropical clawed frog slc29a1 (61% identical), Drosophila melanogaster Ent1 (32% identical). Paralogues in human: SLC29A2 (48% identical), SLC29A3 (32% identical), SLC29A4 (23% identical).